CD5 (CD5 molecule)
Diseases named in the same sentence as CD5 in open-access papers (continued):
Sharing a sentence is not in itself a finding about the gene and the disease.
Chronic lymphocytic leukemia (continued). "Chronic lymphocytic leukemia (CLL) is characterized by the accumulation of monoclonal mature B cells with a CD5+CD19+CD20dimIgdimCD23+CD43+CD27+ surface phenotype in the circulation." (PMID 29069762, 2017). "Chronic lymphocytic leukemia (CLL) is characterized by an accumulation of monoclonal CD5+ mature B-cells in the lymphoid tissues, bone marrow and peripheral blood." (PMID 28881725, 2017). "Chronic lymphocytic leukemia (CLL) is a mature B-cell neoplasm characterized by the expansion of CD5-positive lymphocytes in peripheral blood." (PMID 27110362, 2016). "It should be emphasized that CD5 is also highly expressed on B-cell chronic lymphocytic leukemia (B-CLL)." (PMID 27515534, 2016). "CD5(+) allow us to differentiate chronic lymphocytic leukemia from small lymphocytic lymphoma or mantle cell lymphoma." (PMID 26956381, 2016). "B cell chronic lymphocytic leukemia is characterized by a progressive accumulation of monoclonal mature CD5+ B cells within lymphoid organs and in the peripheral blood." (PMID 27101369, 2016). "Fetal and neonatal B cells as well as CD5+ B cells from healthy adults and from patients with chronic lymphocytic leukemia and autoimmune diseases such as rheumatoid arthritis and SLE were shown to produce natural IgM autoreactive Abs." (PMID 26209442, 2015). "Chronic lymphocytic leukemia (CLL) is the most prevalent leukemia in the West with an accumulation of clonal CD5+/CD19+/CD23+ B cells in the blood, bone marrow, lymph nodes, and spleen." (PMID 26562161, 2015). "Chronic lymphocytic leukemia (CLL) is characterized by the accumulation of malignant CD5+ B lymphocytes in the peripheral blood and lymphoid tissues." (PMID 26540567, 2015). "Chronic lymphocytic leukemia (CLL) is an indolent lymphoproliferative disorder characterized by the progressive accumulation of monoclonal CD5+ B cells in the peripheral blood, bone marrow and secondary lymphoid tissues." (PMID 25699074, 2015). "Chronic lymphocytic leukemia (CLL) is characterized by the accumulation of malignant CD5+ B lymphocytes in the peripheral blood and their progressive infiltration of lymphoid tissues." (PMID 24956101, 2014). "Chronic lymphocytic leukemia (CLL) is a malignant disease characterized by the accumulation of clonal CD5+CD19+ B-cells in the peripheral blood and lymphoid organs." (PMID 25179679, 2014). "Chronic lymphocytic leukemia (CLL) is a malignant disease characterized by the proliferation of CD5+CD23+ B cells." (PMID 25280001, 2014). "In 30% of cases, the lymphocytes show some degree of CD5 expression, which can be confused with chronic lymphocytic leukaemia (CLL)/small lymphocytic lymphoma or mantle cell lymphoma as also observed in our case." (PMID 24171046, 2013). "Chronic lymphocytic leukaemia (CLL) is characterized by accumulation of monoclonal B cells CD5+ in hematopoietic organs, which reflects a defect in apoptosis." (PMID 23637769, 2013). "Chronic lymphocytic leukemia (CLL) is a malignancy of monoclonal CD5+ B cells, which accumulate in the blood, marrow, and lymphoid tissues." (PMID 23840319, 2013). "Chronic lymphocytic leukemia (a B-cell malignancy due to clonal proliferation of a CD5+ subpopulation), a common hematologic malignancy especially among elderly (above 50 years of age) in the Western world, has the most common association with PNP." (PMID 23316398, 2012). "B-CLPD patients who express CD5 are usually patients with chronic lymphocytic leukemia (CLL) or mantle cell lymphoma (MCL), which is rarely met the marginal zone lymphoma." (PMID 31803290, 2012). "Mantle cell lymphoma (MCL) and chronic lymphocytic leukaemia (CLL) belong to the group of CD5-positive small B-cell neoplasms." (PMID 21457541, 2011). "Chronic lymphocytic leukemia (CLL) is characterized by the accumulation of CD5+ B lymphocytes in the blood, bone marrow (BM) and secondary lymphoid tissues." (PMID 21876768, 2011).
Chronic lymphocytic leukemia (continued). "Chronic lymphocytic leukemia (CLL) is a common disorder characterized by the monoclonal accumulation of B lymphocytes with a distinct phenotype (CD5-positive, CD23-positive, CD22-negative and low level of surface Ig) and a highly variable clinical course." (PMID 21897877, 2011). "B-cell CLL, the most common adult leukemia in the Western hemisphere, is characterized by the accumulation of neoplastic B-lymphocytes co-expressing CD5 and CD19 antigens." (PMID 20686606, 2010). "Of note, the lymphocyte turnover is also reduced in other lymphoaccumulative diseases such as, CLL (chronic lymphocytic leukemia), a B CD5+ chronic leukemia in human (J. Defoiche, submitted)." (PMID 17362524, 2007). "Here, we report a proof-of-concept study aimed at the development of an electrical transducer based on PNA-modified ZnONWs for the label-free monitoring of the DNA sequence (cDNA) corresponding to a short fragment of the mRNA of CD5, a prognostic marker of the chronic lymphatic leukemia." (PMID 33670746, 2021). "In this work, the surfaces of ZnONWs are modified by covalent bioconjugation of a peptidic nucleic acid (PNA) probe whose sequence is properly chosen to recognize a complementary DNA (cDNA) strand corresponding to a tract of the CD5 mRNA, the main prognostic marker of chronic lymphatic leukemia." (PMID 33670746, 2021). "Chronic lymphocytic leukemia (CLL) is a lymphoproliferative malignancy of clonally expanded heterogeneous pool of neoplastic B cells with aberrant expression of CD5, which are highly variably distributed between bone marrow, lymphoid organs, and peripheral blood." (PMID 32802894, 2020). "Here we report that upon transplantation of a well-defined aggressive murine B220+CD5+ Chronic Lymphocytic Leukemia (CLL) cell clone, TCL1-192, into SCID mice one injection of a monoclonal antibody directed against SLAMF6 (αSlamf6) abrogates tumor progression in the spleen, bone marrow and blood." (PMID 27029059, 2016). "Immunohistochemically, malignant MALT lymphoma cells express markers of B-cell lineage, but are distinct from follicular lymphomas (which express CD10), mantle cell lymphomas (which express cyclin D1 and CD5), and small lymphocytic lymphomas (which express CD5 and CD23)." (PMID 21892966, 2011). "Chronic Lymphocytic Leukemia (CLL) is immunophenotypically defined as a malignancy of CD5/CD19/CD23 positive, CD20 and Ig dim B cells that manifests with bone marrow failure, lymphadenopathy and infections as a consequence of disease-associated immune suppression." (PMID 20532179, 2010). "Chronic lymphocytic leukemia (CLL), the most commonB cell leukemia in adult Caucasians, is characterized by the expansion of a monoclonal population of CD5+ B lymphocytes." (PMID 36769644, 2023). "Chronic lymphocytic leukemia (CLL) is a hematologic malignancy characterized by progressive accumulation of a rare population of CD5+ B-lymphocytes in peripheral blood, bone marrow, and lymphoid tissues." (PMID 38067115, 2023). "B-cell chronic lymphocytic leukemia (CLL) is a mature B-cell neoplasm characterized by the progressive accumulation of a rare population of mature B-lymphocytes (classified as CD19+CD5+) in the blood and lymphoid organs." (PMID 38067115, 2023). "Chronic Lymphocytic Leukemia (CLL) is characterized by the accumulation of monoclonal CD5+ B cells with low surface immunoglobulins (IG)." (PMID 35837088, 2022). "Chronic lymphocytic leukemia (CLL) is characterized by the clonal expansion of mature, CD5 positive B lymphocytes in the blood, marrow, lymphoid tissue and occasionally in other organs." (PMID 36498556, 2022). "Allelic combinations of the CD5 rs2241002 and rs2229177 SNPs resulting in hyper-reactivity to TCR stimulation are associated to more severe systemic lupus erythematosus (SLE) forms, but predict better prognosis in chronic lymphocytic leukemia (CLL) and melanoma." (PMID 36211446, 2022).
Chronic lymphocytic leukemia (continued). "Chronic lymphocytic leukemia (CLL) is a malignancy disease characterized by the expansion of CD5+ B-1 cells." (PMID 33659046, 2021). "Chronic lymphocytic leukemia (CLL), the most common leukemia in the Western world, is clinically defined by the accumulation of dysfunctional CD5+ B cells." (PMID 33659046, 2021). "Chronic lymphocytic leukemia (CLL) is a clonal expansion of monomorphic, mature, immunologically incompetent CD5+ B-cells in peripheral blood, bone marrow, and secondary lymphoid organs." (PMID 33606850, 2021). "B-cell chronic lymphocytic leukemia (B-CLL) is characterized by progressive accumulation of monoclonal, small, mature-appearing CD5+ B-cells in the peripheral blood, bone marrow and secondary lymphoid tissue." (PMID 31122288, 2019). "Chronic lymphocytic leukemia (CLL) is characterized by the clonal expansion of small mature-looking CD19+ CD23+ CD5+ B-cells that accumulate in the blood, bone marrow, and lymphoid organs." (PMID 29670635, 2018). "B-cell chronic lymphocytic leukemia (CLL) is characterized by clonal proliferation and accumulation of mature CD5+ B lymphocytes in bone marrow, peripheral blood, and lymphoid tissues." (PMID 29670635, 2018). "B-cell chronic lymphocytic leukemia (CLL) is a genetically heterogeneous neoplasm characterized by the progressive accumulation of CD5+ mature B cells in bone marrow, lymph nodes, and blood." (PMID 29390452, 2017). "Chronic lymphocytic leukemia (CLL) is characterized by the accumulation of clonally derived mature CD5+CD19+CD23+CD20+ B cells in the blood, bone marrow, and secondary lymphoid organs." (PMID 27693386, 2017). "Chronic lymphocytic leukemia (CLL) is characterized by the accumulation of mature CD5+ B cells in blood." (PMID 29069762, 2017). "B-cell chronic lymphocytic leukemia (CLL), the most common blood cancer in the Western countries, is characterized by accumulation of neoplastic, small B lymphocytes expressing CD5, CD19 and CD23 in bone marrow, peripheral blood and other lymphoid tissues." (PMID 26517243, 2015). "B-cell chronic lymphocytic leukemia (B-CLL) occurs in elderly patients and is characterized by proliferation and accumulation of monoclonal B lymphocytes, expressing CD5, CD20 and CD23 molecules." (PMID 25218117, 2014). "B-cell chronic lymphocytic leukemia (CLL), which is characterized by a progressive accumulation of leukemia cells that co-express CD5 and CD19 surface antigens, is the most common hematologic malignancy in the Western hemisphere." (PMID 23750211, 2013). "The atypical lymphocytes were immunohistochemically positive for CD20, Bcl-2, CD23, and CD5 consistent with B-cell chronic lymphocytic leukemia/small lymphocytic lymphoma (B-CLL/SLL)." (PMID 24385769, 2013). "B-cell Chronic Lymphocytic Leukemia (CLL) is characterized by the accumulation of malignant clonal CD5+ CD23+ B cells." (PMID 21941553, 2012). "Immunohistochemical staining showed CD20, CD5, and CD23 positivity, with Cyclin D1 negativity, confirming a diagnosis of small lymphocytic lymphoma (SLL) as a result of chronic lymphocytic leukemia (CLL)." (PMID 40897945, 2026). "CLL and its tissue counterpart, small lymphocytic lymphoma (SLL), represent mature B-cell neoplasms characterized by the progressive accumulation of immunophenotypically aberrant CD5+CD19+CD23+ B lymphocytes." (PMID 40868091, 2025). "TCL1 mice are the most commonly used preclinical model for chronic lymphocytic leukemia (CLL), a B-cell malignancy characterized by clonal CD5+ B-lymphocyte accumulation." (PMID 41214147, 2025). "Chronic lymphocytic leukemia (CLL), the most common adult leukemia in Western countries, arises from clonal expansion of CD5+/CD19+ mature B-cells in the blood, bone marrow, and lymphoid tissues due to disrupted apoptosis and proliferation mechanisms." (PMID 40520181, 2025).
Chronic lymphocytic leukemia (continued). "The neoplastic cells show a characteristic immunophenotype (CD5+, CD23+, CD10−, CD43+, weak CD20, weak surface IgM), identical to that found in chronic lymphocytic leukemia." (PMID 38534887, 2024). "Chronic lymphocytic leukemia (CLL) is characterized by clonal expansion of malignant, mature-like CD5+ B cells and is the most common adult leukemia in the Western world." (PMID 39474602, 2024). "Chronic lymphocytic leukemia (CLL) is a hematologic neoplasm of memory B cells characterized by the clonal proliferation and accumulation of mature and typically CD5-positive B cells within the blood, bone marrow, lymph nodes, and/or spleen." (PMID 37726507, 2024). "Considering that both TC and RK mice models develop mature B-cell lymphoma originating from the B1-cell lineage, specifically chronic lymphocytic leukemia (CLL), we assessed B1-cell expansion in peripheral blood using CD19 and CD5 surface markers." (PMID 39198400, 2024). "Chronic lymphocytic leukemia (CLL) is a B-cell neoplasm characterized by typical CD19, CD5, CD20, and CD23 immunophenotypes, as well as kappa or lambda light chain restrictions." (PMID 38338868, 2024). "Two days later, a rapid and unexpected increase inthe lymphocyte count led to further investigations that highlighted a population of CD5+ monoclonal B cellswith a count above clinical parameters for chronic lymphocytic leukemia (CLL), leading to a new CLL diagnosis." (PMID 36769644, 2023). "Marked by the accumulation of small mature CD5+/CD19+/CD23+ B-lymphocytes in the peripheral blood, bone marrow, spleen and lymph nodes, chronic lymphocytic leukemia (CLL) is the most diagnosed leukemia in adults of Western countries." (PMID 37822925, 2023). "Chronic lymphocytic leukemia (CLL) or small lymphocytic lymphoma (SLL), the most common leukemia in adults, is characterized by the expansion of monoclonal CD5+CD23+ B cells in peripheral blood (PB), lymphoid tissues, and bone marrow." (PMID 38258066, 2023). "Hyperproliferative diseases such as Chronic Lymphocytic Leukemia (CLL) and Systemic Lupus Erythematosus (SLE) are potentially related to some disturbance in the apoptosis pathway, specifically in B-1a cells (CD5+)." (PMID 36879336, 2023). "A distinction from follicular lymphoma (positive for CD10 and BCL6), mantle cell lymphoma (CD5, cyclin D1, and SOX11), and chronic lymphocytic leukemia (CD5, CD23, and LEF1) is needed." (PMID 35053607, 2022). "Chronic lymphocytic leukemia (CLL) is the most common leukemia in the adult population of the Western world and typically manifests as an increase in CD5+ve, CD23+ve clonal B cells with low surface immunoglobulin (sIg) expression in the peripheral blood." (PMID 35158929, 2022). "B-cell chronic lymphocytic leukemia (B-CLL), the most frequent type of leukemia in adults, is characterized by the clonal expansion of mature CD5+ B-lymphocytes that accumulate in peripheral blood, bone marrow, and lymphatic tissues." (PMID 35358273, 2022). "Chronic lymphocytic leukemia (CLL), the most common lymphoid malignancy in Western countries, is characterized by the accumulation of monoclonal CD5+ B cells in peripheral blood, bone marrow and secondary lymphoid organs." (PMID 35392232, 2022). "Chronic lymphocytic leukemia (CLL) is originated from clonal expansion of mature B cells expressing the B1 and T cell marker CD5." (PMID 35455931, 2022). "Chronic lymphocytic leukemia (CLL) is a hematologic malignancy characterized by the progressive accumulation of monoclonal, mature-appearing CD5+ B cells in the peripheral blood, bone marrow, and secondary lymphoid organs." (PMID 36016925, 2022). "CD20 positive small B cell neoplasms with simultaneous co-expression of CD5 and CD23 were identified as small lymphocytic lymphoma." (PMID 36405938, 2022). "Chronic lymphocytic leukemia (CLL), a mature and monoclonal CD5+ CD23+ B cell malignancy, proliferates and accumulates in the bone marrow, blood, and lymphoid nodes." (PMID 36186463, 2022).
Chronic lymphocytic leukemia (continued). "Human and mouse chronic lymphocytic leukemia (CLL) develop from CD5+ B cells." (PMID 35455931, 2022). "Chronic lymphocytic leukemia (CLL) is characterized by the clonal proliferation and accumulation of abnormal mature B cells, typically CD5 positive, in the blood and lymphoid tissues." (PMID 35884436, 2022). "B-cell chronic lymphocytic leukemia (B-CLL), the most frequent adult low-grade lymphoproliferative disorder, is characterized by the accumulation of tumor CD5 B cells with enhanced survival potential." (PMID 35203305, 2022). "Chronic lymphocytic leukemia (CLL) is the most prevalent lymphoproliferative disorder in the United States and Europe and is characterized by the clonal expansion of mature CD5+ CD23+ B cells." (PMID 34108958, 2021). "Chronic lymphocytic leukemia (CLL), the most frequent leukemia in the USA and Europe, is characterized by the massive accumulation of mature CD5+ B cells in the bone marrow, blood, and lymph nodes." (PMID 35008790, 2021). "Chronic lymphocytic leukaemia and small lymphocytic lymphoma (CLL/SLL) are characterized by the clonal expansion of CD5 + B cells." (PMID 34625709, 2021). "Chronic lymphocytic leukemia (CLL) is the most common adult leukemia in the Western world and is characterized by the accumulation of clonal CD5+/CD19+ B cells in peripheral blood, lymph nodes, spleen and bone marrow." (PMID 34206399, 2021). "Chronic lymphocytic leukemia (CLL) is a malignancy of mature, antigen-experienced B cells with a distinct immunophenotype (CD5+CD23+sIglow)." (PMID 34209724, 2021). "High expression of LAG-3 has also been shown in chronic lymphocytic leukemia cells (CLL), characterized by clonal expansion of mature B-cells (CD5+ CD23+ CD27+ Iglow)." (PMID 34067904, 2021). "Flow cytometry confirmed the presence of an abnormal B-cell population consistent with B-cell chronic lymphocytic leukemia, with the following markers: CD19+, CD20+, CD23+, CD5+, CD10-." (PMID 33274154, 2020). "Chronic lymphocytic leukemia (CLL) is considered an antigen-driven B-cell neoplasm, characterized by clonal expansion of mature CD5+ B-lymphocytes." (PMID 32570839, 2020). "Chronic lymphocytic leukemia (CLL) is a B-lymphoproliferative disease, which consists of the abnormal proliferation of CD19/CD5/CD20/CD23 positive lymphocytes in blood and lymphoid organs, such as bone marrow, lymph nodes and spleen." (PMID 32937811, 2020). "Chronic lymphocytic leukemia (CLL) is characterized by the accumulation of small and mature CD5+ B cells in blood, bone marrow and secondary lymphoid organs." (PMID 32676504, 2020). "Chronic Lymphocytic Leukemia (CLL) is the most common leukemia in the Western countries, characterized by the clonal expansion of CD5+ B cells in peripheral blood, lymph-nodes and bone marrow." (PMID 33194757, 2020). "Chronic lymphocytic leukemia (CLL), the most common leukemia in the western world, is characterized by a progressive expansion of relative mature B lymphocytes, CD19+/CD5+/CD23+, in peripheral blood, secondary lymphoid tissues, and in bone marrow (BM)." (PMID 30642077, 2019). "Chronic lymphocytic leukemia (CLL) is the most common B-cell neoplasm in Europe and United States, characterized by progressive accumulation of monoclonal CD5+ B cells in peripheral blood, bone marrow, and peripheral lymphoid organs." (PMID 30948927, 2019). "On the other hand, mantle cell lymphomas (MCLs) and a subset of chronic lymphocytic leukemia (CLL) with unmutated IGHV are thought to derive from naive B cells and pre-GC mature B cells expressing the CD5 surface marker." (PMID 31681423, 2019). "SEMA4D/CD100 was found to be expressed in B-cell chronic lymphocytic leukemia (CLL) cells and in normal CD5+ B lymphocytes, and its high-affinity receptor Plexin-B1 was found in BM stromal cells, follicular dendritic cells, and activated T lymphocytes." (PMID 31143707, 2019).